MAZ (MYC associated zinc finger protein)
Diseases named in the same sentence as MAZ in open-access papers (continued):
Sharing a sentence is not in itself a finding about the gene and the disease.
pancreatic cancer (6 papers, 2019 to 2023). "A large number of studies have found that MAZ plays a vital role in the progression of a variety of cancers including breast, prostate and pancreatic cancer." (PMID 34183010, 2021). "MAZ is a downstream molecule of Cyr61/CCN1, which expands the invasion of pancreatic cancer cells through CRAF-ERK signaling." (PMID 36890610, 2023). "MAZ, which is a downstream molecular of the Cyr61/CCN1, promotes pancreatic cancer cell invasion via CRAF-ERK signaling." (PMID 34183010, 2021). "In contrast, NDRs in primary pancreatic cancer-specific enhancers involved in enhancer-promoter loops are enriched for motifs for TFs such as E2F1, MAZ, and ZFX." (PMID 34348759, 2021). "The MAZ, which is a downstream gene of the oncoprotein Cyr61/CCN1, promotes pancreatic cancer cell migration and invasion via CRAF-ERK signaling." (PMID 34183010, 2021).
Alzheimer disease (5 papers, 2008 to 2022). A progressive, neurodegenerative disease characterized by loss of function and death of nerve cells in several areas of the brain leading to loss of cognitive function such as memory and language. "Enrichment was also seen amongst genes whose upregulation is associated with Alzheimer’s disease, and the longest DMR we discovered, which is in the MAZ gene, is amongst this gene set and is known to localize to pathologic structures in Alzheimer’s disease brain." (PMID 34857913, 2022). "Expression of the mouse homolog of MAZ is increased in an Alzheimer’s disease mouse model." (PMID 34194426, 2021). "ZF87/MAZ and FAC1 co-localize to pathologic structures in Alzheimer's disease brain." (PMID 25379732, 2014).
gastric cancer (5 papers, 2020 to 2025). A primary or metastatic malignant neoplasm involving the stomach. "Pan‐cancer analysis of MAZ expression and prognostic significance was performed using The Cancer Genome Atlas (TCGA) data, with emphasis on its divergent prognostic impact in gastric cancer (GC)." (PMID 40411278, 2025). "However, high expression of MAZ is most significantly associated with better prognosis in gastric cancer (GC)." (PMID 40411278, 2025). "Taken together, these data clarify that the FOXK1/MAZ axis can represent an effective therapeutic target for regulating autophagy to reverse gastric cancer EMT progression in an acidic microenvironment." (PMID 32268297, 2020). "Inhibition of MAZ can significantly inhibit cell migration of gastric cancer." (PMID 36988258, 2023).
glioma (4 papers, 2022 to 2025). A benign or malignant brain and spinal cord tumor that arises from glial cells (astrocytes, oligodendrocytes, ependymal cells). "One mechanism identified is through stimulated binding of the cytokine IL-13 to its receptor IL-13α2 in macrophages, and another through association with CD44 leading to Myc-associated zinc finger protein (MAZ) activity in glioma stem cells." (PMID 40769579, 2025). "Downregulated expression of TUG1 and upregulated expression of MAZ were identified in DHA treated glioma cells." (PMID 36164395, 2022). "The results showed that TUG1 overexpression can increase the mortality of DHA treated glioma cells, which can be reversed by MAZ overexpression, confirming the resistant mechanism by this pathway." (PMID 36164395, 2022). "After construction of TUG1-overexpressed U87 and U251 glioma cells, as expected, the expression of MAZ and FTH1 at the protein level was significantly downregulated." (PMID 36164395, 2022). "Downregulated expression of TUG1 and upregulated expression of MAZ were confirmed in DHA treated glioma cells." (PMID 36164395, 2022). "Current studies have shown that MAZ is related to the permeability of blood tumor barrier, angiogenesis, apoptosis, migration, and invasion of gliomas." (PMID 36164395, 2022). "AQP1 may be implicated in glioma formation by interacting with the transcriptional regulation networks involving the FOXO4, MAZ, and E2F1/2." (PMID 38057925, 2023). "Besides, MAZ overexpression increased the inhibitory effect of DFO on ferroptosis in DHA treated glioma cells." (PMID 36164395, 2022). "Finally, we observed the effects of TUG1 overexpression alone, MAZ overexpression alone, and both TUG1 and MAZ overexpression on cytotoxicity of DHA in glioma cells." (PMID 36164395, 2022).
leukemia (4 papers, 2017 to 2021). A malignant (clonal) hematologic disorder, involving hematopoietic stem cells and characterized by the presence of primitive or atypical myeloid or lymphoid cells in the bone marrow and the blood. "We set the cutoff of the signal binding normalized scores (in the range of 0–1000) to 350 and identified promyelocytic leukemia (PML), cyclin T2 (CCNT2) and MYC-associated zinc finger protein (MAZ) as binding to both the +157 enhancer and the promoter of the VEGFA gene." (PMID 34316716, 2021). "Overall, this analysis shows the importance of experimental validation of the GRN, because a central node such as MAZ does not appear to be important for leukemia survival." (PMID 34088716, 2021). "In leukemia, SIOMICS discovered two shared motifs that were similar to the motifs of MAZ and SP1." (PMID 28684851, 2017).
liposarcoma (4 papers, 2015 to 2022). A usually painless malignant tumor that arises from adipose tissue. "To investigate potential cooperation of SPIN1 and MAZ in liposarcoma, we analyzed genome-wide chromatin association of MAZ by ChIP-seq." (PMID 25749382, 2015). "Analysis of 155 patient samples revealed that levels of GDNF, activated RET (RETph), and MAZ were elevated in all four types of liposarcoma." (PMID 25749382, 2015). "In accordance with these results, we observe increased levels of GDNF, activated RET, and MAZ in human liposarcoma compared to normal adipose tissue or lipoma." (PMID 25749382, 2015). "Our mechanistic studies in vitro and in xenograft mouse models demonstrate that SPIN1, in cooperation with the transcription factor MAZ, controls proliferation and apoptosis of liposarcoma cells by directly regulating expression of the RET signaling pathway effector GDNF." (PMID 25749382, 2015). "Together, these data suggest that MAZ and SPIN1 cooperate to regulate GDNF expression in T778 cells and that MAZ, at least in part, contributes to SPIN1-mediated control of liposarcoma cell proliferation and apoptosis." (PMID 25749382, 2015). "To investigate the relevance of our observations for human disease, we stained tissue samples from liposarcoma patients with GDNF, RETph, or MAZ antibody and determined the immune reactive scores." (PMID 25749382, 2015). "Accordingly, knockdown of SPIN1 or MAZ results in reduced levels of GDNF and activated RET explaining diminished liposarcoma cell proliferation and survival." (PMID 25749382, 2015).
Arthritis (3 papers, 2006 to 2019). Inflammation of a joint. "Targeting SAF-1/MAZ can also benefit other diseases that are linked with aberrant expression of VEGF, including arthritis, defective wound repair, endometriosis, and blindness." (PMID 25449683, 2015).
liver cancer (3 papers, 2020 to 2025). An epithelial or non-epithelial malignant neoplasm that arises from the liver. "This yielded 32 candidate TFs, of which MAZ (MYC Associated Zinc Finger Protein) was ranked among the highest according to the probability of survival in liver cancer patients." (PMID 40860182, 2025). "We also observed enhanced MAZ condensation in all 8 tested liver cancer samples versus matched normal liver tissues, suggesting clinical relevance of MAZ phase separation." (PMID 38316778, 2024). "Here, the authors revealed that G4s drive molecular motility in phase-separated condensates of MAZ and coactivators, leading to activated CCND1 expression in liver cancer." (PMID 38316778, 2024). "Recent studies have shown that MAZ, as an oncogene, can promote EMT in liver cancer cells, but whether the inhibition of MAZ in an acidic microenvironment is involved in the regulation of autophagy and EMT in GC cells is not well known." (PMID 32268297, 2020). "When examining MAZ levels in liver cancer, we observed increased MAZ expression in various HCC cell lines and 8 liver cancer samples, compared to nontumorigenic hepatic HL-7702 cells and matched normal liver tissues, respectively." (PMID 38316778, 2024).
schizophrenia (3 papers, 2010 to 2024). A major psychotic disorder characterized by abnormalities in the perception or expression of reality. "MAZ was also identified as a blood biomarker in schizophrenia." (PMID 25379732, 2014).
atherosclerosis (2 papers, 2017 to 2022). A disease characterized by the build-up of fatty material and calcium deposition in the arterial wall resulting in partial or complete occlusion of the arterial lumen. "This provides the first confirmed clinical association between MAZ-Ab OD and clinically apparent atherosclerosis." (PMID 29209328, 2017). "Taking a proven ACS as unequivocal evidence of atherosclerosis, this study clearly demonstrates a difference in MAZ-Ab OD on ELISA between these patients and healthy controls." (PMID 29209328, 2017). "The exact autoimmune role of MAZ-Ab in atherosclerosis may be related to plaque macrophage activity but more research into the pathophysiological function of MAZ is needed." (PMID 29209328, 2017). "MAZ, as a transcriptional activator, may participate in the development of atherosclerosis." (PMID 36324511, 2022). "MAZ-Ab OD may be a better marker for atherosclerosis than myocardial damage." (PMID 29209328, 2017).
bladder cancer (2 papers, 2011 to 2019). "In addition, HRas is silenced by two neighbouring G-quadruplexes and activated by MAZ in bladder cancer cells." (PMID 31488180, 2019).
colitis (2 papers, 2016 to 2023). Inflammation of the colon. "Myc-associated zinc-finger (MAZ) increases tumorigenesis of colitis-associated CRC and promotes the growth of human CRC cell lines." (PMID 37305392, 2023).
lung adenocarcinoma (2 papers, 2023 to 2025). A carcinoma that arises from the lung and is characterized by the presence of malignant glandular epithelial cells. "The transcription factor, MYC associated zinc finger protein (MAZ), functions as an upstream regulator of NEIL3 to directly promote its transcription and this induces cisplatin resistance in lung adenocarcinoma." (PMID 40761744, 2025). "In lung cancer, MAZ promotes cisplatin resistance in lung adenocarcinoma cells by inhibiting DNA damage." (PMID 38086789, 2023). "Previous study showed that MAZ promoted chemoresistance in lung adenocarcinoma cells by inhibiting DNA damage." (PMID 38086789, 2023). "The transcription factor, MAZ, increases NEIL3 expression and inhibits DNA damage in lung adenocarcinoma cells, thereby promoting cisplatin resistance in the lung adenocarcinoma cells." (PMID 40761744, 2025).
prostate tumor (2 papers, 2015 to 2016). "Our current findings suggested the expression of ZNF217 was transcriptional activated by MAZ in prostate tumor cells." (PMID 27768596, 2016).
acute coronary syndrome (1 paper, 2017). Signs and symptoms related to acute ischemia of the myocardium secondary to coronary artery disease. "This study compares MAZ-Ab OD on ELISA testing among patients presenting with acute coronary syndromes (ACSs) to healthy controls and investigates the association of MAZ-Ab to traditional CVD risk factors." (PMID 29209328, 2017).
Anophthalmia (1 paper, 2020). Absence of the globe or eyeball. "Several cases of CNVs associated with anophthalmia/microphthalmia were reported in the literature in the 16p11.2 chromosomal region, where MAZ is located." (PMID 32571845, 2020).
bone metastasis (1 paper, 2019). Transfer of a neoplasm from its primary site to bones. "High expression of MAZ positively correlates with poor overall and bone metastasis-free survival in PCa patients." (PMID 31488180, 2019). "MAZ expression was elevated in PCa tissues with bone metastasis (T4–6) compared with expression in PCa tissues without bone metastasis and was further increased in metastatic bone tissues (T7–9); consistently, protein expression of KRas and activated RalA exhibited the same pattern." (PMID 31488180, 2019).
bone tumor (1 paper, 2019). "At the same time, MAZ-silencing VCaP cells exhibited less osteoblastic area of bone tumors, as well as a longer bone tumor burden-free survival time compared with the scramble group." (PMID 31488180, 2019). "The analysis of IHC staining showed that upregulating MAZ enhanced, while silencing MAZ repressed HRAS and KRAS expression in the bone tumor tissues from tibia in different mice groups, confirming the positive correlation of MAZ with HRAS and KRAS in these PCa cells." (PMID 31488180, 2019).
cardiac hypertrophy (1 paper, 2012). "Taken together, our study suggests that MAZ is an important TF for both types of cardiac hypertrophy." (PMID 22523601, 2012).
chronic myeloid leukemia (1 paper, 2016). "MAZ is an inflammation-responsive transcription factor up-regulated during chronic myeloid leukemia." (PMID 27386562, 2016).
Cirrhosis (1 paper, 2008). A chronic disorder of the liver in which liver tissue becomes scarred and is partially replaced by regenerative nodules and fibrotic tissue resulting in loss of liver function. "While normal and peritumoral non-cirrhotic liver, cirrhosis and CCC showed a similar MAZ expression (p = 0.3112, by one-way ANOVA), significantly increased expression could be found in HCC (p = 10-4, by one-way ANOVA)." (PMID 18400094, 2008).
clear cell renal cell carcinoma (1 paper, 2021). "However, the biological roles and clinical significance of MAZ in clear cell renal carcinoma (ccRCC) remain unclear." (PMID 34183010, 2021).
cone-rod dystrophy (1 paper, 2020). Inherited retinal dystrophies that belong to the group of pigmentary retinopathies. "Seven of the 37 individuals with MAZ variants (19%) were affected with different eye disorders (including cone-rod dystrophy, rapid progressive vision loss, retinitis pigmentosa, congenital cataracts and optic nerve hypoplasia)." (PMID 32571845, 2020).
inflammatory bowel disease (1 paper, 2025). A spectrum of small and large bowel inflammatory diseases of unknown etiology. "For example, in inflammatory bowel disease, PlncRNA1 overexpression protects intestinal barrier function by regulating the expression of Myc-associated zinc finger protein (MAZ), ZO-1 and Occludin." (PMID 40338929, 2025).
influenza (1 paper, 2012). An acute viral infection of the respiratory tract, occurring in isolated cases, in epidemics, or in pandemics; it is caused by serologically different strains of viruses (influenzaviruses) designated A, B, and C, has a 3-day incubation period, and usually lasts for 3 to 10 days. "Thus, there are multiple interactions involving MAZ which we feel are suitable targets to mitigate inflammation during moderate to highly pathogenic influenza infections." (PMID 22937776, 2012). "The MAZ transcription factor activity adds an additional layer of complexity between influenza infection-induced apoptosis, immune cell trafficking, and the observed cell cycle arrest." (PMID 22937776, 2012).
ischemia (1 paper, 2019). A hypoperfusion of the BLOOD through an organ or tissue caused by a PATHOLOGIC CONSTRICTION or obstruction of its BLOOD VESSELS, or an absence of BLOOD CIRCULATION. "Concomitantly, immunohistochemistry demonstrated that macrophages in the subcapsular sinus in deep and superficial CLNs increased TNF-α expression after focal ischemia, this response was suppressed by MAZ treatment." (PMID 31757960, 2019).
lipoma (1 paper, 2015). A benign, usually painless, well-circumscribed lipomatous tumor composed of adipose tissue. "Furthermore, staining of adipose tissue, lipoma, WDLS, MLS, DDLS, or PLS samples taken from one patient with SPIN1, GNDF, RETph, or MAZ antibody showed that also in individual patients high levels of SPIN1 correlate with high levels of GDNF, RETph, or MAZ." (PMID 25749382, 2015).
lymphoma (1 paper, 2017). A malignant (clonal) proliferation of B- lymphocytes or T- lymphocytes which involves the lymph nodes, bone marrow and/or extranodal sites. "In lymphoma, SIOMICS found four motifs similar to the motifs of SP1, MAZ, GC and the CAC-binding protein, respectively." (PMID 28684851, 2017).
male infertility (1 paper, 2021). The inability of the male to effect fertilization of an ovum after a specified period of unprotected intercourse. "Three genes associated with genitourinary birth defects and male infertility are MYC-associated zinc finger protein (MAZ), CRK-like proto-oncogene (CRKL), and E2F transcription factor 1 (E2F1), which are discussed in this section." (PMID 34552771, 2021).
myeloma (1 paper, 2021). "Six TFs (CXXC1, BPTF, MAZ, KLF13, CBFB and RFX5) were identified as showing higher connectivity in all myeloma subgroups compared to ND PC, thus exemplifying the process of existing TF ‘re-wiring’ in MM." (PMID 34521827, 2021).
osteosarcoma (1 paper, 2021). A usually aggressive malignant bone-forming mesenchymal neoplasm, predominantly affecting adolescents and young adults. "Taken together, we concluded that CRC LLPS inhibition significantly reduced metastasis at least partly via the MAZ in osteosarcoma." (PMID 34432948, 2021). "Our results showed that depletion of MAZ reduced osteosarcoma invasive activity and inhibited the metastasis in the orthotopic tumor xenograft mouse model." (PMID 34432948, 2021). "As a newly identified SE‐driven gene in metastatic osteosarcoma, the biological roles of MAZ in osteosarcoma remain unclear." (PMID 34432948, 2021). "The downstream targets of MAZ in osteosarcoma need to be further identified." (PMID 34432948, 2021).
rectal tumors (1 paper, 2021). "MAZ is a hypoxia tolerance induction TF, which would be required substantially in the colon and rectal tumors." (PMID 34934770, 2021).
scrapie (1 paper, 2010). A fatal disease of the nervous system in sheep and goats, characterized by pruritus, debility, and locomotor incoordination. "A recent study of microRNA signature of prion-induced neurodegeneration has shown that EGR1, E2F1 and MAZ might be also implicated in the putative deregulation of immune response related genes by miRNAs via modulation of transcriptional regulators in scrapie-infected mice." (PMID 20405009, 2010).